TNF (tumor necrosis factor)
Diseases named in the same sentence as TNF in open-access papers (continued):
Sharing a sentence is not in itself a finding about the gene and the disease.
tumor (continued). "In cancerous cells, NF-κB is often constitutively activated, promoting the expression of pro-inflammatory cytokines such as tumor necrosis factor-alpha (TNF-α), interleukin-1β (IL-1β), and cyclooxygenase-2 (COX-2), which contribute to tumor growth and metastasis." (PMID 39861761, 2025). "The data presented here suggest that dasatinib may be an effective agent for reducing the secretion of IFN-γ and TNF-α by activated CAR123, thereby reducing CD123 upregulation on endothelial cells and minimizing the on-target/off-tumor effect of CAR123." (PMID 41477551, 2025). "Notably, depletion of ASNS also increased the infiltration of CD8+ T cells in tumor parenchyma and enhanced their cytokine production including GZMB, TNF-α, and IFN-γ." (PMID 39964752, 2025). "The lack of changes in TNFα and IFNγ receptors suggests limited neutrophil involvement in these anti-tumor pathways." (PMID 40867260, 2025). "In addition, the inactivation of GPX4 triggered by FG-CDs@Cu enhances the sensitivity of tumor cells to IFN-γ and TNF-α, forming a “positive ferroptosis-immunity cycle”, which reduced the tumor volume by 67% in a model of lung metastasis of melanoma." (PMID 40559667, 2025). "Interestingly, the dominant CD45+ hematopoietic cell type within the CD45+ IFN-γ+ and TNF-α+ population was CD11b+ myeloid cells, which are enriched in the CD8+ T cell–sufficient tumor microenvironment." (PMID 40553564, 2025). "Thus, interactions between TNF-α and endothelial cells play a central role in CRC pathogenesis by driving inflammatory, mesenchymal, and pro-metastatic alterations in the tumor microenvironment." (PMID 40558596, 2025). "Interestingly, these tumour cell subpopulations all exhibit activation of the Wnt pathway, while showing lower activity in the EGFR, MAPK, NFκB, or TNF-α pathway." (PMID 39877290, 2025). "In addition, TNFα and IFN-γ produced by CD8+ T cells help to eliminate tumor cells by inducing apoptosis and inhibiting tumor growth." (PMID 40243755, 2025). "This team of researchers has studied the capabilities and properties of the drug NGR-TNF, a fusion of the peptide Cys-Asn-Gly-Arg-Cys-Gly (CNGRCG, denoted as NGR) and the cytokine TNF-α, and the ligand of aminopeptidase N (CD13) of tumor-blood-vessel-positive (+) blood vessels." (PMID 40331982, 2025). "In addition, the synergistic action of IFN-γ and tumor necrosis factor alpha (TNF-α) can promote tumor cell senescence, inhibit tumor cell proliferation, and contribute to the remodeling of the tumor vasculature." (PMID 40725022, 2025). "In addition, TNF-α activates the M2-type polarization of TAMs and secretes inhibitory factors such as IL-10 and TGF-β, further suppressing anti-tumor immune responses." (PMID 41376630, 2025). "TNF-α induces the overexpression of programmed death ligand 1 (PD-L1) in a variety of tumors, creates an immunosuppressive TME, weakens the inhibitory effect of immune checkpoints, and induces tumor cells to develop resistance to targeted therapy." (PMID 41346580, 2025). "Additionally, cytokines such as IL-6, IL-8, IL-10, TNF-α, and TGF-β demonstrate context-dependent activities, intricately regulating immune responses, tumor growth, and metastasis." (PMID 40909271, 2025). "To confirm this, we used quantitative PCR on tumor specimens, which showed elevated TNF-α mRNA levels in the BI group compared to Non-BI counterparts." (PMID 39865310, 2025). "Mast cell migration in the tumor microenvironment is induced by the expression of several growth factors, proinflammatory cytokines, and molecules, such as chemokines, prostaglandins SCF, TGF, TNF, and FES kinase." (PMID 40075893, 2025). "Elevated levels of certain cytokines, such as IL-6, IL-17, and IL-8, have been linked to tumor progression, whereas others, including IL-1, TNF-α, TGF-β, and IFN-α, play a role in suppressing HPV replication and tumor growth, especially during the early stages." (PMID 40142865, 2025).
tumor (continued). "Additionally, the concurrent administration of TNF and anti-CD40 mAb boosts neutrophil activation and toxicity, further promoting tumor cell apoptosis and clearance by enhancing oxidative damage and N1 neutrophil recruitment in the TME." (PMID 39925807, 2025). "They express the CCR2, CCR5, and CXCR2 chemokine receptors, which are then mobilized to the blood and tumor by chemokine ligands (CCL2, CCL5, CXCL1-8) and other inflammatory mediators like prostaglandin E2 (PGE2) generated by TME, VEGF, TGF-β, TNF-α, and IL-1β, IL-6, and IL-10." (PMID 40727443, 2025). "Our findings that TRUB1 knock-down inhibits BIRC3 expression, along with the suppression of TNFα signaling via NFκB, underscore the role of BIRC3 in CRC tumor progression and suggest that TRUB1 may regulate CRC growth through BIRC3-dependent mechanisms." (PMID 40260225, 2025). "In addition, dysregulation of pyroptosis-related genes induces aberrant cell-cell communication in tumor tissues and mediates ligand-receptor interactions between various cell types in UCEC via the TNF signaling pathway to promote cancer progression." (PMID 39744500, 2025). "Functionally, SPP1+ TAMs play a central role in promoting tumor cell epithelial-mesenchymal transition (EMT), angiogenesis, intravasation, metastasis, and immunosuppression through the secretion of factors including SPP1, CCL18, CXCL8, TNF-α, and IL-1β." (PMID 41459510, 2025). "This concept could partly explain the strong correlation of TNF-α with CA72-4 and CA19-9 in our study: these markers and the cytokine might be interlinked in driving tumor aggressiveness." (PMID 40299527, 2025). "Furthermore, co‐injection of BMDMsPRDX1‐KO or RAW264.7PRDX1‐KD cells inhibited syngeneic tumor growth by enhancing CD8+ T‐cell cytotoxicity and secretion of TNF‐α and GzmB." (PMID 41306557, 2025). "CAAs differ from “normal” adipocytes as they display fibroblast-like morphology, usually contain several dispersed small lipid droplets, and produce increased amounts of inflammatory cytokines IL-1β, IL-6, IL-8, TNF, chemokines (CCL2, CCL5), and leptin, which altogether facilitate tumor progression." (PMID 40940764, 2025). "Flow cytometry analysis of tumor‐infiltrating CD8+ T cells revealed that cotreatment with V‐9302 and anti‐PD‐1 significantly enhanced the expression of cytolytic proteins (GZMB and PRF1) and effector cytokines (IFN‐γ and TNF‐α) compared to monotherapy groups." (PMID 40575936, 2025). "Indeed, NR4A2/A1R engineered CAR T cells exhibited significantly increased expression of IFNγ, TNF and IL-2 secretion, primarily in CD8+ CAR T cells, following tumor cell coculture." (PMID 40610421, 2025). "They exert CAR-mediated cytotoxicity, where engagement of the scFv with its target tumor antigen triggers intracellular signaling that leads to the release of cytotoxic granules (perforins and granzymes) and pro-inflammatory cytokines (IFN-γ and TNF-α)." (PMID 40643499, 2025). "In both MC38 and 18.5 (not shown) models, tumor‐infiltrating Tregs and Tconvs displayed bright intracellular expression of total TNF and TNFR2, respectively." (PMID 40977146, 2025). "In the tumor microenvironment of the solid tumor, tumor-infiltrating lymphocytes kill cancer cells by producing cytokines, such as, interferon-gamma (IFN-γ), granzyme B, and tumor-necrosis factor-alpha (TNF-α)." (PMID 40169858, 2025). "•SB in the EAC mice model reduced the tumor-specific markers (CEA, TNF-α, IL-6)." (PMID 40712409, 2025). "Moreover, CD4 T cells with cytotoxicity contribute to the tumor microenvironment by secreting cytokines such as IFN-γ and TNF-α, which enhance immune activation and disrupt immune suppression." (PMID 40959273, 2025). "cDC1s also secrete tumor necrosis factor (TNF)-α, IL-6, IL-12, and type I interferons (IFN-I) to amplify immune cell activation, while their production of CXCL9 and CXCL10 recruits T cells to tumor sites." (PMID 40924040, 2025).
tumor (continued). "Subsets such as Vγ9Vδ2 and Vδ1+ T cells mediate anti-tumor responses via perforin/granzyme-dependent cytolysis and through engagement of death receptors (e.g., FasL, TRAIL), along with secretion of IFN-γ and TNF to promote effector cell recruitment and antigen presentation." (PMID 40660400, 2025). "To validate this hypothesis, we performed multiplex immunofluorescence staining in tumor specimens and confirmed the proximal co-localization of IL34-positive tumor cells and TNF-α+ TAMs." (PMID 39865310, 2025). "Tumor rejection is accompanied by antigen spreading, abscopal effects, and infiltration by clonally diverse T cells, dendritic cells, and MHC I/II+ macrophages producing CXCL9/10, CCL5/8, and TNF." (PMID 41256707, 2025). "While most anti-tumor effects of DCs occur through their activation of cytotoxic cells, DCs can also directly signal to tumor cells and induce cell death through TRAIL, nitric oxide, perforin, granzyme B and TNFα." (PMID 40663561, 2025). "Subsequently, the levels of TNF, IL-12 and IFN-γ were detected in tumor tissues." (PMID 40296909, 2025). "Tc cells are essential markers of the anti-tumor immune response, inducing apoptosis of target cells via cytotoxin release (such as perforin and granzyme B) and producing pro-inflammatory cytokines, like IFN-γ and TNF-α." (PMID 40136347, 2025). "Additionally, high-dose UVA triggered activation of p38 MAPK, upregulation of TNFα, and the regulatory signaling molecule Connective Tissue Growth Factor (CTGF) mRNA expression, while transcription of tumor-suppressors VDR, and P2RX7 were downregulated." (PMID 40328921, 2025). "Among the pretreatment covariates ranked by multivariate analysis, preinfusion TNF-α, product T-naive phenotype, TMTV, and FLIPI score ranked as top ones in their respective categories of serum analytes, product attributes, tumor features, and clinical biomarkers." (PMID 40536814, 2025). "Furthermore, both molecules enhance the release of immunosuppressive cytokines such as TGF-β and IL-10, while decreasing the generation of pro-inflammatory cytokines such as TNF-α and IFN-γ, which ultimately aids in creating an immunosuppressive tumor milieu." (PMID 40867265, 2025). "TRAIL/TNFSF10 is a member of the tumor necrosis factor (TNF) death ligand family that selectively initiates extrinsic apoptosis in caspase-8-dependent tumor cells without affecting normal cells." (PMID 40230861, 2025). "TNF-α drives inflammatory signaling that fosters cellular proliferation and differentiation, whereas TGF-β has a dual role—promoting epithelial–mesenchymal transition (EMT) and suppressing immune responses, thereby enhancing tumor invasiveness." (PMID 39857670, 2025). "Furthermore, downregulating LINC00886 reduces the expression of TLR4, Myd88, phosphorylated NF-κB p65, and PD-L1, while increasing TNF-α and IFN-γ levels and enhancing CD8 + T cell antitumor activity, thereby reducing tumor cell immune escape." (PMID 40999508, 2025). "Additionally, the Ganoderma atrum polysaccharide (PSG-1) activated macrophages and increased the production of TNF-α, IL-1β, and NO via p38 MAPK in the murine CT26 tumor model." (PMID 41019059, 2025). "Regarding tumor markers, CA72-4 showed the most significant elevation (4.9 [3.1–7.9] vs. 2.4 [1.8–4.2] U/mL, p < 0.001), followed by CA19-9 (12.1 [6.1–25.1] vs. 6.4 [3.2–10.6] U/mL, p = 0.030) and TNF-α (4.5 [2.8–11.4] vs. 2.9 [1.7–5.7] pg/mL, p = 0.014)." (PMID 40299527, 2025). "LIF levels were markedly elevated in the C26 tumor milieu, whereas other known wasting factors (IL-6, TNF-α, myostatin) were not, indicating that LIF is the key wasting cytokine in this model." (PMID 40869331, 2025). "Moreover, increased expression levels of cytokines, including TNF, IL-12 and IFN-γ, were observed in H101-treated or combination-treated tumor tissues." (PMID 40296909, 2025).
tumor (continued). "These cells respond to tumor-specific antigens by producing effector cytokines like IFN-γ and tumor necrosis factor-alpha (TNF-α), which stimulate cytotoxic activity and enhance the recruitment of other immune cells, such as CD8+ T cells and natural killer cells, to the tumor site." (PMID 40066439, 2025). "Hypoxia within the tumor microenvironment drives T-cell exhaustion by activating hypoxia-inducible factors (HIFs), such as HIF-1α, which epigenetically suppress cytotoxic cytokines (e.g., IFN-γ, TNF-α)." (PMID 40001572, 2025). "The release of IFN-γ, TNF-α, and GZMB further enhanced tumor cell killing." (PMID 40281554, 2025). "Notably, the interaction between TNF-α and HMGCR is significant in several diseases, providing new theoretical bases and potential therapeutic targets for tumor treatment." (PMID 41450917, 2025). "For instance, hsa_circ_0072309 modulates tumor immune infiltration via activation of the PI3K-AKT/Ras pathway, whereas circMAN1A2 (hsa_circ_0000118) influences gastric cancer progression by inhibiting CTL secretion of cytokines such as TNF-α and IFN-γ." (PMID 41229433, 2025). "TNF‐α, a member of the TNF receptor superfamily, serves as an intermediator of the immune system, safeguarding the host from the attacks of countless infections as well as tumor cells, and stimulates the death of tumor cells via apoptosis." (PMID 41498028, 2025). "While TNF‐α can inhibit tumor cell growth by inducing apoptosis in cancer cells, it also stimulates the proliferation, survival, migration, and angiogenesis of most cancer cells that are resistant to TNF‐α induced cytotoxicity, leading to tumor development." (PMID 40859961, 2025). "This suggests that while IFN-γ-driven responses play a crucial role in eliminating tumor cells, the simultaneous overexpression of PCNA and TNF-α may act as an adaptive mechanism for immune evasion and resistance to immune-mediated cytotoxicity." (PMID 40430573, 2025). "These alterations are considered to be driven by changing circulating cytokines and chemokines profiles released by malignant cells such as TNFα, EGFR ligands, transforming growth factor‐beta (TGF‐β) and IL-6, contributing to local immune evasion and tumor progression." (PMID 38965182, 2025). "By inhibiting pro-inflammatory cytokines like tumor necrosis factor (TNF)-α and IL-6, these compounds may reduce the chronic inflammation that fuels tumor growth." (PMID 40507159, 2025). "Moreover, key cytokines and chemokines, including IL-6, IL-10, IL-8, TNF-α, TGF-β, and CCL2/5, demonstrate subtype-specific and context-dependent effects, acting as both tumor-promoting and tumor-suppressing agents through complex signaling networks." (PMID 40909271, 2025). "In addition to improved phenotypes and tumor-killing efficiency, hypoxia-conditioned PIM3 KO CAR-T cells also secreted more IFN-γ, TNF-α, and granzyme B after being stimulated with tumor cells." (PMID 41199316, 2025). "Furthermore, we observed that gp350-CAR-T cells secreted large amounts of IFN-γ and TNF-α when co-cultured with EBV + tumor cells, indicating their ability to trigger a robust anti-tumor immune response." (PMID 39930509, 2025). "FC analysis further revealed that the combination of USP25 overexpression and anti-PD-1 therapy markedly reduced the accumulation of MDSCs, but strongly increased the number of tumor-infiltrating functional CD8+ T cells, including Granzyme B+ T cells, IFN-γ+ T cells, and TNF-α+ T cells." (PMID 41326342, 2025). "In the absence of CD14+ TAMs, human CD4+ T cells responded to tumor antigen with TNF production (first column)." (PMID 40872773, 2025). "This vaccine format not only induced robust dendritic cell maturation but also significantly increased pro-inflammatory cytokines like TNF-alpha, IFN-gamma, and IL-12 in plasma and tumor tissues, leading to enhanced infiltration of CD4+ and CD8+ T cells into the tumor microenvironment." (PMID 40160263, 2025).
tumor (continued). "Additionally, when co-cultured with tumor cells, BBζ-Neo exhibited higher levels of IFNγ, IL-1β, IL-6, MCP-1, TNF-α and IL-8 compared to BBζ." (PMID 40025022, 2025). "Following coculture with E0771-Her2 tumor cells, A1R CAR T cells exhibited significantly increased production of IFNγ and TNF and increased expression of effector related genes PD-1 (Pdcd1), TIM-3 (Havcr2), Gzmb and Irf4 compared to control and A3R CAR T cells." (PMID 40610421, 2025). "CD20+ subpopulation, known to secrete cytokines and chemokines that activate the STAT3/NF-κB signaling pathway, leading to increased expression of pro-inflammatory mediators, including IL-6, TNF-and IFN-γ, and MMP-9, which facilitate tumor invasion and metastasis." (PMID 40821783, 2025). "Compared to CAR-T cells that exert their cytotoxic functions by both chimeric antigen and T cell receptors, CAR-NKT cells promote indirect anti-tumoral effects by stimulating dendritic cell maturation and activation of tumor-infiltrating CD8+ lymphocytes and NK cells via TNF-α and IFN-γ release." (PMID 40002679, 2025). "Despite a robust biological rationale linking TNF-α to tumor progression, inflammation, and therapy resistance, no significant clinical benefit has been demonstrated in trials to date." (PMID 41007766, 2025). "Adenosine combined with A2aR can inhibit the production of macrophages, reduce the secretion of different pro-inflammatory mediators such as TNF-α and VEGF, inhibit the attack of immune cells on tumor cells, and help tumor cells to escape immune system control." (PMID 40420185, 2025). "Beyond intrinsic tumor factors, the tumor microenvironment's excessive secretion of pro‐inflammatory cytokines, such as IFN‐γ, tumor necrosis factor α (TNF‐α), and interleukins (IL), can induce PD‐L1 expression in tumor cells, thereby facilitating immune escape." (PMID 40135791, 2025). "A subsequent cytokine release assay with PBMCs showed that, although ETA-067 does not induce IFN-γ or TNF-α release, the CD3 bispecific molecule caused tumor anchor-independent production of both cytokines after 24 hours of culture." (PMID 40755782, 2025). "Moreover, neutrophil activation (e.g., via TNF, a CD40 agonist, or tumor-targeting antibodies) induced tumor eradication through oxidative damage." (PMID 40563651, 2025). "TNF‐α‐mediated activation of NF‐kB led to increased expression of various angiogenic factors, including VEGF, IL‐8, and basic fibroblast growth factor (bFGF), promoting tumor angiogenesis." (PMID 39805002, 2025). "CAAs secrete chemokine ligands CCL2 and CCL5, interleukin-1 (IL-1), interleukin-6 (IL-6), tumor necrosis factor-α (TNF-α), and vascular endothelial growth factor (VEGF), and promote cell aggressiveness, tumor progression, migration, and chemotherapy resistance." (PMID 40141437, 2025). "In BC cells, the signaling pathways TNFα/NFκB and IL6/STAT3 are known to promote tumor progression via activation of key EMT-related transcription factors, such as Snail Family Transcriptional Repressor 1 (Snail1), Twist-related protein 1 (Twist1), and Zinc finger E-box binding homeobox 1 (ZEB1)." (PMID 40807456, 2025). "The administration of arjunolic acid in this study led to a significant reduction in pro‐inflammatory cytokines such as TNF‐α, IFN‐γ, and IL‐6, along with lower levels of VEGF (a key factor in tumor angiogenesis) and a marked increase in anti‐inflammatory cytokine IL‐10." (PMID 40908716, 2025). "Subsequent analyses on the interactions between tumor cells and CD8+ effector T cells saw that the CCL chemotaxis signaling, major histocompatibility complex-I antigen presentation signaling, and IFN-II/TNF tumor killing signaling were all reduced in RAC1A159V tumors." (PMID 41160695, 2025). "Comparably, RNA‐seq analysis revealed that CD8+ T cells exhibited upregulated TNF‐α expression upon DMXAA stimulation, which may have contributed to tumor immunity." (PMID 39573933, 2025).